FSCN2 (fascin actin-bundling protein 2, retinal)
Description:
Acts as an actin bundling protein. May play a pivotal role in photoreceptor cell-specific events, such as disk morphogenesis.
Synonyms: RP30; RFSN
Tractability: No criterion of Open Targets' tractability assessment is met for any kind of drug.
Gene: Protein-coding gene on chromosome 17 (81,528,377 to 81,537,130, forward strand). Ensembl gene ENSG00000186765.
Subcellular location: Cytoplasm, cytoskeleton; Cell projection, stereocilium
Pathways (Reactome):
Sensory Perception: Sensory processing of sound by inner hair cells of the cochlea; Sensory processing of sound by outer hair cells of the cochlea
Gene Ontology:
Molecular function: protein binding; actin binding; actin filament binding; protein-macromolecule adaptor activity
Biological process: actin cytoskeleton organization; actin filament bundle assembly; anatomical structure morphogenesis; cell migration; establishment or maintenance of cell polarity; visual perception; actin filament organization
Cellular component: actin cytoskeleton; cytoplasm; cytoskeleton; stereocilium
Genetic constraint (gnomAD): Loss-of-function variants: 46 observed, 32.75 expected, observed/expected ratio (o/e) 1.4, 90% interval 1.11 to 1.78. The synonymous counts are far from expectation, so gnomAD's model fits this gene poorly and the ratio says little. Missense variants: 844 observed, 649.93 expected, observed/expected ratio (o/e) 1.3, 90% interval 1.23 to 1.38. Synonymous variants: 351 observed, 268.37 expected, observed/expected ratio (o/e) 1.31, 90% interval 1.2 to 1.43.
Homologues: Orthologues: macaque FSCN2 (98% identical), guinea pig FSCN2 (93% identical), rat Fscn2 (92% identical), mouse Fscn2 (91% identical), dog FSCN2 (91% identical), pig FSCN2 (85% identical), chimpanzee FSCN2 (76% identical), tropical clawed frog fscn2 (66% identical), zebrafish fscn2b (64% identical), zebrafish fscn2a (62% identical), Drosophila melanogaster sn (38% identical). Paralogues in human: FSCN1 (57% identical), FSCN3 (27% identical).
Diseases named in the same sentence as FSCN2 in open-access papers:
FSCN2 is named in the same sentence as 19 diseases in open-access papers, as found by Europe PMC text mining. Sharing a sentence is not in itself a finding about the gene and the disease. The quoted sentences say what the papers report.
Hearing impairment (6 papers, 2018 to 2024). A decreased magnitude of the sensory perception of sound. "Mutations in Fscn2 gene have been linked to hearing impairment and retinal degeneration in humans and mice." (PMID 38374196, 2024). "We have screened 2-5 mice per strain across 54 BXD strains and confirmed QTL on Chr 11 where Fscn2 is identified as a causal gene of hearing loss and found 1 novel QTL on Chr 16 in aged BXD mice that is most likely an ahp locus in BXD strains." (PMID 32587610, 2020). "We also identified rare coding associations in fascin actin-bundling protein 2 (FSCN2) and synaptojanin 2 (SYNJ2) with increased risk for hearing loss, both of which were recently observed in UKB18." (PMID 35661827, 2022). "Conditioning on His138Tyr attenuated the significance of the burden test (P = 3 × 10−6 after conditioning on His138Tyr) but did not eliminate the signal, suggesting that other variants in FSCN2 may increase the risk for hearing loss." (PMID 35661827, 2022). "Five of the variants that have rare genotypes with large effects are at loci that have not been reported for any type of hearing impairment: FBF1, FSCN2, C10orf90, SH2D4B, and TBX2." (PMID 34108613, 2021). "Unlike those of the Fscn2+/+ mice, the ABR thresholds in the Fscn2−/− mice had already significantly risen at stimulus frequencies of 16 and 32 kHz by age 3 weeks, which indicated an early onset of hearing impairment for high frequencies." (PMID 30082328, 2018).
deafness (4 papers, 2018 to 2024). An inherited or acquired condition characterized by the complete loss of the ability to hear from one or both ears. "The Fscn2 knockout (Fscn2-/-) mice showed progressive hearing loss starting at 3 weeks after birth, making it a new hereditary deafness mouse model." (PMID 38374196, 2024). "The results in the Fscn2−/− mice demonstrated progressive hearing loss starting at age 3 weeks, leading to near deafness at age 24 weeks." (PMID 30082328, 2018). "Twenty-five genes were present in both male and female hearing difficulty high variant load lists, including seven deafness genes (CLIC5, MYH14, COL9A3, ELMO3, FSCN2, GJB2, SLC26A5)." (PMID 35761239, 2022).
retinal degeneration (4 papers, 2014 to 2024). Degeneration of the retina. "Mutations in the Fscn2 gene can lead to hearing impairment in mice and retinal degeneration in humans." (PMID 38374196, 2024). "The results revealed that the Fscn2 gene plays an essential role in mouse ears and eyes; mice with the null mutation of Fscn2 develop progressive hearing loss and retinal degeneration." (PMID 30082328, 2018). "Group (b) was very small with only 9 genes, and it did not make a cluster of functionally related GO terms, although 6 of 9 genes were annotated as causal genes for retinal degeneration (Abca4, Elovl2, Fscn2, Nxnl1, Pde6c, and Pde6h)." (PMID 24747725, 2014). "In Mfrprd6 eyes, a significant 1.5- to 2.0-fold decrease was observed among transcripts of genes linked to retinal degeneration, including those involved in visual cycle (Rpe65, Lrat, Rgr), phototransduction (Pde6a, Guca1b, Rgs9), and photoreceptor disc morphogenesis (Rpgrip1 and Fscn2)." (PMID 25357075, 2014). "Lastly, we showed that the Fscn2−/− mice served as a new mouse model for retinal degeneration." (PMID 30082328, 2018).
retinitis pigmentosa (3 papers, 2016 to 2023). Retinitis pigmentosa (RP) is an inherited retinal dystrophy leading to progressive loss of the photoreceptors and retinal pigment epithelium and resulting in blindness usually after several decades. "FSCN2 has been found in retinal photoreceptor cells and its splicing variants might be related to retinitis pigmentosa and hearing loss." (PMID 37891374, 2023). "To date, the only reported link between FSCN2 and retinal disease is a single bp deletion (rs376633374) that was identified in Japanese subjects with either retinitis pigmentosa or macular dystrophy." (PMID 27628848, 2016). "Earlier studies showed that the Fscn2 gene was related to retinal pigmentosa in humans and mice." (PMID 30082328, 2018).
autosomal dominant retinitis pigmentosa (2 papers, 2018 to 2022). Autosomal dominant retinitis pigmentosa (RP) is an autosomally dominant inherited retinal dystrophy leading to progressive loss of the photoreceptors and retinal pigment epithelium and resulting in blindness usually after several decades. "FSCN2 was firstly associated to autosomal dominant retinitis pigmentosa (RP) in the Japanese population." (PMID 34996991, 2022). "Earlier studies showed that a deletion mutation in human FASCIN2 (FSCN2) gene could cause autosomal dominant retinitis pigmentosa." (PMID 30082328, 2018). "It has been reported that 208delG in FSCN2 correlated with autosomal-dominant retinitis pigmentosa and autosomal-dominant macular degeneration in the Japanese population." (PMID 30082328, 2018).
age-related hearing loss (1 paper, 2024). "Fscn2−/− mouse is a typical model of age-related hearing loss which exhibits progressive hearing impairment and outer hair cell death from 3 weeks of age, as well as a progressive degeneration of spiral ganglion neurons from 4 weeks to 40 weeks of age, especially at basal turns." (PMID 38374196, 2024).
infection (1 paper, 2024). The state of being infected such as from the introduction of a foreign agent such as serum, vaccine, antigenic substance or organism. "HEI-OC1 cells with low level expression of the Fscn2 gene were created by infection with lentiviral particles expressing Fscn2-shRNA." (PMID 38374196, 2024).
FSCN2 also shares sentences with these, for which no sentence is quoted: Macular dystrophy (2 papers); ciliopathy (1); cone dystrophy (1); congenital stationary night blindness (1); macular degeneration (1); melanoma (1); myeloma (1); retinal disease (1); retinal dystrophies (1); retinopathies (1); tumor (1); virus infection (1).